IL6 (interleukin 6)
Diseases named in the same sentence as IL6 in open-access papers (continued):
Sharing a sentence is not in itself a finding about the gene and the disease.
rheumatoid arthritis (continued). "In the hypoxia microenvironment of rheumatoid arthritis tissue, monocytes secreted several inflammatory factors, such as IL-6, TNF-α, IL-1β and MMP-3, which contributed to the joint inflammation in RA." (PMID 29456830, 2018). "Over the last 30 years, the treatment of rheumatoid arthritis (RA) has been revolutionized with the development of biologic therapies such as anti-TNF, anti-IL-6, CTLA4-Ig and anti-CD20 agents, among others." (PMID 30886973, 2018). "Indeed, despite not being disease specific, IL-6 has been shown to be more sensitive than other serum cytokines for the prediction of therapeutic response of rheumatoid arthritis patients." (PMID 28152087, 2017). "Moreover, the serum levels of pro-inflammatory cytokines that persist in rheumatoid arthritis including interleukin IL-1β, IL-6 and IL-10 were decreased, although the level changes had not reached statistical significance." (PMID 27658047, 2016). "Tocilizumab, a humanized anti-interleukin-6 (IL6) receptor antibody, is an established treatment for moderate to severe active rheumatoid arthritis (RA) which cannot be adequately controlled by conventional disease-modifying antirheumatic drugs (DMARDs)." (PMID 27818807, 2016). "However, CXCL8 and CCL20 enhanced osteoblast-mediated osteoclastogenesis, partly via IL-6 production, suggesting that CXCL8 and CCL20 may contribute to osteoporosis in rheumatoid arthritis by affecting bone cell communication." (PMID 26103626, 2015). "The effect of LP99 on IL-6 expression demonstrates for the first time that a small-molecule BRD7/9 inhibitor may have a similar function and utility to IL-6 neutralizing antibodies, such as tocilizumab, in the treatment of rheumatoid arthritis." (PMID 25864491, 2015). "IL-6, together with transforming growth factor- (TGF-) β, induces differentiation of IL-17-producing T helper cells (Th17) that play a crucial role in the development of various autoimmune diseases including systemic lupus erythematosus, Behçet's disease, or rheumatoid arthritis." (PMID 26640809, 2015). "The clinical efficacy of specific cytokine inhibitors in rheumatoid arthritis (RA) reveals the pivotal role of predominantly monocytic cytokines like IL-1β, TNF or IL-6 in the pathogenesis of the disease." (PMID 26251236, 2015). "Importantly, research into T cells in rheumatoid arthritis has led to novel treatments to treat this disease such as the TNF-α inhibitor, etanercept and IL-6 antagonist tocilizumab which inhibit or neutralize TNF-α and IL-6 respectively." (PMID 25501574, 2014). "TNF-α, IL-6 and LIF also contribute to tissue erosion in advanced stages of OA, although their implication in rheumatoid arthritis (RA) prevails." (PMID 22051322, 2011). "Rheumatoid Arthritis drugs recommended by The American College of Rheumatology (ACR) fall into several categories: small molecule DMARDs including methotrexate, lefluonamide and others; anti-TNF-α agents; T-cell activation modulators; IL-6 antagonists; IL-1 antagonists; and B-cell directed therapy." (PMID 21423713, 2011). "Changes in plasma IL-6, plasma VEGF and serum YKL-40 were determined in rheumatoid arthritis (RA) patients during treatment with etanercept alone or in combination with methotrexate." (PMID 20029652, 2009). "Although JAK inhibitors are in use for the treatment of rheumatoid arthritis and other inflammatory diseases, it must be emphasized that JAKs do not selectively inhibit IL-6 signaling pathway and off-target effects may interfere with other cytokines or growth factors that utilize JAK/STAT pathway." (PMID 40114923, 2025). "Rheumatoid Arthritis (RA): Especially in non-acute phases, H2S inhibits fibroblast-like synoviocyte proliferation, reduces IL-6 and MMP-3 production, and blocks NF-κB activation, thereby reducing joint destruction." (PMID 41226825, 2025).
rheumatoid arthritis (continued). "However, studies have shown that Segatella abundance is increased in rheumatoid arthritis (RA), and its potential role in the pathogenesis of RA may involve stimulating helper T cell (Th) 17 populations and inducing the production of Th17 cell-related cytokines (IL-6 and IL-23)." (PMID 41321822, 2025). "We aimed to investigate the expression of pro-inflammatory cytokine genes TNFA, IL6, IL12B, IL23, IL18 and immunoregulatory genes FOXP3, TGFB1, and IL10 in the peripheral blood of patients with rheumatoid arthritis (RA) at messenger ribonucleic acid (mRNA) level." (PMID 38534783, 2024). "Substantial studies have demonstrated that IL-6 is involved in a variety of autoimmune and chronic inflammatory diseases, such as inflammatory bowel disease (IBD), diabetes, rheumatoid arthritis (RA), multiple sclerosis, asthma and most recently, COVID-19 pneumonia." (PMID 37025289, 2023). "Gastrodia elata Blume (GE) is a traditional Chinese herbal medicine with anti-inflammatory activity, and according to a study, GE significantly decreased the IL-6, CXCL8, MMP-3 and MMP-13 levels in TNF-induced rheumatoid arthritis fibroblast-like synoviocytes (RA-FLSs)." (PMID 36439173, 2022). "Interestingly, we found that IL-6 levels were significantly elevated in ITP patients when compared with healthy controls, which is consistent to the other reports showing that IL-6 upregulation is related to autoimmune diseases, such as rheumatoid arthritis, multiple sclerosis, and asthma." (PMID 35665326, 2022). "The co-activation of NF-κB and JAK2/STAT3 induce a massive and sustained production of proinflammatory cytokines, such as IL-6 and IFN-γ, which are critical for the development of inflammatory diseases including rheumatoid arthritis (RA) and multiple sclerosis (MS)." (PMID 35246140, 2022). "Whilst the role of IL-6 may be secondary compared to IL-1β for the development of pathology in the K/BxN STIA model, its inhibition leads to therapeutic benefit in experimental and human rheumatoid arthritis, as both cytokines are key therapeutic targets to stop disease progression." (PMID 36505403, 2022). "Additionally, it has been proposed that TNF-α-induced IL-6 and IL-8 production in FLS from patients with rheumatoid arthritis (FLS-RA) is dependent on L-lactate levels." (PMID 35095895, 2021). "Furthermore, overexpression of IL-6, IL-10, IL-17, and TNF-α, among others, is important in the pathogenesis of SLE, polymyositis (PM), dermatomyositis (DM) and rheumatoid arthritis (RA) and is significantly related to disease activity." (PMID 33882880, 2021). "Furthermore, the proinflammatory cytokines IL-6, TNF-α, IFN-γ, and IL-12 play such an important inductor of inflammation in disorders such as severe/uncontrolled asthma, Alzheimer's disease, and rheumatoid arthritis and may be considered a predictive factor for treatment failure." (PMID 32351323, 2020). "Interleukin-6 (IL-6) is involved in fibroblast-like synoviocyte (FLS) activation and promotes pannus formation and bone and cartilage destruction in rheumatoid arthritis (RA)." (PMID 33228785, 2020). "Rheumatoid arthritis (RA) physiopathology includes synovial inflammation with proinflammatory cytokine overexpression of such as tumor necrosis factor (TNF), interleukin (IL)-1, IL-6, and IL-171." (PMID 29472591, 2018). "Presently, however, only two monoclonal antibodies (mAbs), tocilizumab (anti–IL-6R) and siltuximab (anti–IL-6), have been approved in the US for the treatment of rheumatoid arthritis (RA) and Castleman's disease respectively, but not for cancer." (PMID 26840088, 2016). "The aims of this study were to do, comparative analysis of the levels of different cytokines such as LIF, TNF-alpha, IL-1, IL-6 and OSM, in the synovial fluid samples aspirated from 10 Rheumatoid arthritis (RA), 25 Osteoarthritis (OA) and 7 Mixed arthropathies (MA) patients." (PMID 21593968, 2008).
rheumatoid arthritis (continued). "In patients with rheumatoid arthritis (RA) treated with 40.50 mg/kg BW/day of MO extract for one month, IL-6 levels and Simplified Disease Activity Index (SDAI) scores significantly decreased, demonstrating MO’s effectiveness in reducing inflammation and disease activity in RA." (PMID 40149610, 2025). "Notably, studies from the last five years have demonstrated that paclitaxel significantly inhibits the migration of rheumatoid arthritis fibroblast-like synoviocytes (RA-FLS) and reduces the production of critical inflammatory mediators, including IL-6, IL-8, and IL-1β." (PMID 41614803, 2025). "In patients with OA, the immunoexpression levels of TNF-α, IL-1β, IL-7, MMP-1, MMP-2, and MMP-3 were significantly higher in patients with active rheumatoid arthritis (RA), whereas the immunoexpression levels of IL-1, IL-2, IL-4, IL-6, IL-15, IL-18, and MMP-3 were not statistically different." (PMID 40004793, 2025). "Compared with healthy people, Tfh cells expression level in rheumatoid arthritis (RA) patients was increased, and Tfh cells proportion was positively correlated with disease activity score in 28 joints (DAS28), phosphorylated STAT3 (pSTAT3) -Tyr705, and plasma IL-6 concentration." (PMID 38051200, 2024). "Recombinant AREG upregulated the mRNA expression levels of vascular endothelial growth factor, IL-8, and IL-6, but not those of IL-1β or TNF-α in rheumatoid arthritis fibroblast-like synoviocytes." (PMID 37868614, 2023). "Several studies showed that MI192 has dose-dependent inhibition for interleukin-6 (IL-6), and peripheral blood mononuclear cells (PBMC) in rheumatoid arthritis (RA) patients but not in healthy control." (PMID 37022380, 2023). "TNFα, IL-1β, and hypoxia also up-regulate the expression of cytokines, including IL-6, CXCL8 (namely, IL-8), CCL2, CXCL11, CXCL12, and VEGF, as well as the expression of cytokine receptors such as TNFRSF9 in synovial fibroblasts derived from rheumatoid arthritis (RA) patients." (PMID 35967331, 2022). "Inflammatory cytokines such as interleukin 6 (IL-6), IL-1β, and tumor necrosis factor (TNF) have been shown to be biomarkers of both acute and chronic CHIKVD, with levels of these cytokines also commonly being elevated in autoimmune arthritides such as rheumatoid arthritis (RA)." (PMID 35254128, 2022). "Since the production of proinflammatory cytokines is increased in rheumatoid arthritis (RA), it has been proposed that the increase in cytokines including IFN-γ and IL-6 could drive the observed decrease in GRK2 expression and activity in MNLs isolated from RA patients." (PMID 33546162, 2021). "In addition to the benefits of exercise-induced IL-6, such as promoting OCN secretion and fatty acid oxidation, it also exacerbates local and systemic osteoclast-mediated bone destruction, including Paget’s disease of bone (PDB), rheumatoid arthritis (RA), and the bone metastasis of breast cancer." (PMID 40563533, 2025). "S100A4 has also been shown to stimulate the production of the pro-inflammatory cytokines IL-1β, IL-6, and TNF-α from peripheral blood mononuclear cells (PBMC) isolated from patients with rheumatoid arthritis; however, these effects were not RAGE-dependent, but TLR-4-dependent." (PMID 39766257, 2024). "Although IL-6 may be another potential target for psoriasis treatment, data in the literature show that attempts to treat psoriasis with tocilizumab (TCZ), a humanized anti-interleukin-6 (IL-6) receptor antibody licensed for the treatment of rheumatoid arthritis (RA), have been unsuccessful." (PMID 36901778, 2023). "In rheumatoid arthritis, the effects of TNF-α and IL-6 are observed regardless of the length of the disease, but in SSc, IL-6 may have a minimal role in patients with a long disease course and IL-13 may have a limited role during the early disease stages." (PMID 34064515, 2021).
rheumatoid arthritis (continued). "On the other hand, age, gender, alcohol consumption, coronary heart disease, rheumatoid arthritis, the use of oral corticosteroids or NSAIDs, body mass index, and the serum proinflammatory markers resistin, hs-CRP, TNF-α, and IL-6 were not significantly related to logLSburden." (PMID 23902899, 2013).
atherosclerosis (1,562 papers, 2004 to 2026). A disease characterized by the build-up of fatty material and calcium deposition in the arterial wall resulting in partial or complete occlusion of the arterial lumen. "IL‐6 has been shown to play an important role in the inflammatory process in atherosclerosis, and elevated levels are associated with CV events." (PMID 41273211, 2026). "High levels of TNF-α and interleukin-6 (IL-6) released from adipose tissue increase the risk of developing atherosclerosis (AS), stimulate the liver to produce more C-reactive protein (CRP), and increase blood pressure." (PMID 41226575, 2025). "Interleukin-6 (IL-6) has been linked to a range of cardiovascular complications, including myocardial ischemia, atherosclerosis, heart failure, and hypertension." (PMID 40940933, 2025). "Multivariable analysis identified the REGICOR score and IL-6 serum levels as independent factors associated with atherosclerosis." (PMID 40718411, 2025). "Elevated levels of IL-6 are associated with an increased risk of cardiovascular events, the progression of atherosclerosis, and poorer prognosis in patients with heart failure." (PMID 40724563, 2025). "Numerous inflammation-associated biomarkers, especially TNF-α and interleukin-6, have been identified as inflammatory biomarkers for monitoring atherosclerosis and cardiovascular risk." (PMID 39941424, 2025). "Activation of the JAK2/STAT3 pathway is strongly linked to the IL‐6 cytokine family, which plays a critical role in endothelial cell dysfunction associated with atherosclerosis." (PMID 40166646, 2025). "Preclinical studies have shown that macrophages deficient in TET2 or DNMT3A drive interleukin (IL)-1β/IL-6 inflammasome activation, thereby promoting atherosclerosis and metabolic dysfunction, whereas the JAK2V617F mutation accelerates thrombosis." (PMID 41516113, 2025). "Research on animals has shown that IL-6 plays a part in the early aggravation of atherosclerosis; in male mice fed a high-fat and regular diet, recombinant IL-6 treatment was linked to the early formation of atherosclerotic plaques." (PMID 40218291, 2025). "For example, in the Multi-Ethnic Study of Atherosclerosis (MESA), both subclinical atherosclerosis and IL-6 were inversely associated with naïve CD4T cells." (PMID 41280118, 2025). "Sleep disturbances associated with somatic symptoms can elevate inflammatory markers (CRP, IL-6), contributing to vascular damage and atherosclerosis, thereby increasing stroke risk." (PMID 41583002, 2025). "Ziltivekimab, a new monoclonal antibody directed against IL-6, has been specifically designed for patients with atherosclerosis and high cardiovascular risk and is being evaluated both in patients with atherosclerosis and CKD and in patients with HFpEF." (PMID 39425816, 2025). "IL-6 has been shown to be positively linked with atherosclerosis and RCTs of treatments targeting the IL-6 pathway (e.g., ziltivekimab) in patients with high risk of atherosclerotic diseases demonstrated a reduction in CV event rates." (PMID 40823190, 2025). "Elevated IL-6 levels are linked to increased cardiovascular risk, as this cytokine promotes the development of atherosclerosis and other vascular complications." (PMID 40184131, 2025). "The role of IL-6 in worsening atherosclerosis has been implicated in numerous experimental murine studies, human cohorts, and genetic studies." (PMID 40497942, 2025). "IL-6 trans-signaling is implicated in vascular dysfunction in RA.Elevated sVCAM-1 is associated with cardiovascular risk and subclinical atherosclerosis progression in RA patients." (PMID 41179568, 2025). "TNFα and IL-6 in particular, are associated with diminishing nitric oxide production and endothelial dysfunction, both known precursor factors for atherosclerosis and CVDs." (PMID 40370477, 2025).
atherosclerosis (continued). "Human epidemiological studies have consistently found that IL‐6 is a risk marker for atherothrombotic events with genetic studies supporting a potential causal role for IL‐6 signaling in atherosclerosis." (PMID 41200383, 2025). "We have recently shown “that macrophages derived from LPS stimulated monocytes in individuals with subclinical atherosclerosis exhibited increased secretion of IL6, IL10 and CCL2, which was associated with intima-media thickness”." (PMID 38441018, 2025). "IL-6 improves risk prediction of atherosclerosis and inflammation in patients with cardiovascular risk." (PMID 41471131, 2025). "Anti-inflammatory properties, reduces proatherosclerotic cytokines (TNF-α, IL-1, IL-6), improves cholesterol efflux, and decreases the risk of atherosclerosis." (PMID 40376321, 2025). "Second, flavonoids in tea can inhibit pro-inflammatory cytokines associated with atherosclerosis (such as IL-6 and TNF-α)." (PMID 40537848, 2025). "In numerous investigations, elevated plasma IL-6 levels have been substantially associated with atherosclerotic plaque instability, establishing IL-6 as a valid marker for atherosclerosis and coronary artery disease (CAD)." (PMID 40218291, 2025). "Evidence suggests that hs-CRP serves as a prognostic marker, while IL-6 and IL-1β play causal roles in the development of atherosclerosis." (PMID 40149635, 2025). "The pro-inflammatory cytokine IL-6 plays a role in several biological activities, including cell proliferation and differentiation and has been implicated in the pathogenesis of atherosclerosis and plaque formation within the vasculature." (PMID 41296388, 2025). "For instance, chronic exposure to high levels of IL‐6 predisposes vascular wall thickening and atherosclerosis." (PMID 38634217, 2024). "The mechanism involves bacteria from the mouth entering the bloodstream, triggering immune responses that elevate systemic inflammation markers, such as C-reactive protein (CRP) and interleukin-6 (IL-6), both of which are also linked to atherosclerosis." (PMID 39677218, 2024). "Elevated blood IL‐6 levels are associated with CVDs, including endothelial dysfunction, arterial stiffness, and atherosclerosis." (PMID 39669190, 2024). "IL-6 is a crucial inflammatory factor associated with the advancement and worsening of atherosclerosis." (PMID 39335642, 2024). "Inflammatory markers such as CRP and IL-6, linked to H. pylori infection, play significant roles in the development of atherosclerosis and CVDs." (PMID 39202269, 2024). "IL‐6 has a crucial association with cardiovascular diseases, including atherosclerosis, hypertension, cardiac fibrosis and cardiomyopathy." (PMID 39160453, 2024). "In a mouse model of atherosclerosis induced by a high-fat diet, oral administration of GRb1 was found to suppress levels of inflammatory factors such as IL-1β, IL-6, and TNF-α in serum, attenuating apoptosis associated with inflammatory activity." (PMID 39339421, 2024). "We concluded that L162V polymorphism in the gene for PPAR-alpha seems to be associated with atherosclerosis through a mechanism including regulation of the interleukin-6 level." (PMID 39062500, 2024). "On the other hand, oxidative stress can result in the production of inflammatory mediators, including interleukin-6 and tumor necrosis factor-alpha, and affect the ovary and endothelium causing anovulation and premature atherosclerosis in PCOS." (PMID 38997723, 2024). "Elevated IL-6 levels are linked to atherosclerosis complications and the progression of cardiac insufficiency, suggesting a significant role for IL-6 in heart failure risk assessment." (PMID 39202593, 2024). "IL-6 plays an important role in regulating the inflammatory response that causes damage to the vascular wall and accelerates atherosclerosis." (PMID 39104587, 2024). "Chronic elevation of IL-6 is linked to the progression of atherosclerosis and can contribute to the development and worsening of cardiovascular diseases." (PMID 39273041, 2024).